ID1 (inhibitor of DNA binding 1)
Diseases named in the same sentence as ID1 in open-access papers (continued):
Sharing a sentence is not in itself a finding about the gene and the disease.
tumor (continued). "Inhibitor of differentiation 1 (ID1) has been described as a cancer-promoting factor and also involved in the formation of an immunosuppressive tumor microenvironment." (PMID 37996458, 2023). "In previous studies, we have shown that Id1 complete abrogation at both host microenvironment and tumor cells sensitized lung tumors to anti-PD-1 therapy, substantially reducing tumor growth." (PMID 37841258, 2023). "We also studied the impact of anti-PD-1 blockade after complete inhibition of Id1 expression (tumor cells and host microenvironment)." (PMID 37841258, 2023). "The inhibitory effects of Id1 deletion in TAMs on both tumor growth and liver metastasis were completely abrogated when Ccl4 and Serpinb2 were depleted simultaneously." (PMID 37996458, 2023). "ID1 has demonstrated roles in GBM tumour progression and the control of NSC quiescence during regenerative neurogenesis." (PMID 34767259, 2022). "In line with this reasoning, we further confirmed that BMP receptor inhibitors successfully suppressed tumor growth, as well as ID1, HIF-1α, VEGFA, and VEGFR2 expression in HCC xenograft tumors." (PMID 35163396, 2022). "ID1 is a stem-cell-like gene that is over-expressed in numerous types of cancers, and it facilitates tumor angiogenesis and metastasis." (PMID 36232920, 2022). "Id1/3-PA7 fused with a cell-protein transduction domain is an anti-tumor agent that triggers cell-cycle arrest and apoptosis in ovarian and breast cancer." (PMID 34302526, 2022). "Blocking EFI2 signaling remarkably decreased the expression of ID1 and attenuated the tumor-formation related phenotypes." (PMID 35941362, 2022). "The overexpression or deregulation of the ID1 gene has been reported to promote tumor development and progression in numerous types of cancers." (PMID 35806401, 2022). "The direct comparison of ID1 mRNA expression in PDAC tissue vs. normal pancreas tissue showed significantly higher ID1 expression in the tumor samples compared to normal tissues (P < 0.05)." (PMID 36627902, 2022). "Signaling pathway analysis revealed that the functions of ID1 dysregulation in tumor progression were mainly mediated by EIF2 signaling, which was commonly reported as a promising target in cancer therapy." (PMID 35941362, 2022). "Previous research has shown that tumor xenograft neurogenesis, angiogenesis, and vascularization are dependent on Id1 and Id3, and Id3 is especially crucial for tumor angiogenesis." (PMID 35599595, 2022). "Cancer cells derived from PDAC tumor tissues that displayed an active TGFβ pathway averted cell apoptosis by transcriptional dysregulation of ID1, also known as an inhibitor of progenitor cell differentiation." (PMID 35941362, 2022). "Baicalein significantly reduced Src phosphorylation in tumor-bearing mice, and these findings highlighted that baicalein inhibited Id1 in an Src-dependent manner." (PMID 35955525, 2022). "In a variety of tumor tissues, such as colorectal cancer, prostate cancer, and cervical cancer, Id1 expression is increased and has a certain correlation with tumor progression." (PMID 35049366, 2022). "High Id1 levels mark tumor cells with high self-renewal capacity, whereas low Id1 levels identify tumor cells with proliferative potential but limited self-renewal capacity." (PMID 34302526, 2022). "Past studies have shown that Id1 can be used as a marker of EPCs to track EPCs in bone marrow, blood, and tumor stroma." (PMID 35049366, 2022). "The maintenance of EndMT status at the tumor metastatic colonization site depends on the Id1 target protein Twist1, while the maintenance of this cell status at the original site depends on Snail1." (PMID 35049366, 2022).
tumor (continued). "Next, we isolated tumor tissues (TT) and adjacent non-tumor tissues (ANTT) from 25 patients with HBV-associated HCC and compared their E2F4, Id1, and HBV expression." (PMID 34975318, 2022). "Α3β1 promotes the expression of ID1, a transcriptional regulator, which plays a role in angiogenesis during embryogenesis and tumor formation, as well as during endothelial morphogenesis in cell culture models." (PMID 35269439, 2022). "Increasing evidence suggests that dysregulation of Id proteins, particularly Id1, Id2, and Id3, is related to advanced tumor grade and a dismal prognosis in a wide range of human cancers." (PMID 35599595, 2022). "To determine the upstream regulators and related canonical signaling pathway involved in the ID1 dysregulation and tumor formation, we applied IPA analysis on the DE genes of PDAC cancer cells from the scRNA-seq analysis." (PMID 35941362, 2022). "In this study, we found that ID1 protein is upregulated in response to HIF1α inhibition, and ID1 in turns supports HIF1-independent tumor growth in hypoxia and in vivo." (PMID 34820369, 2021). "In particular, PD-L1_1 and 10_12 mAbs were found to inhibit the phosphorylation levels of Erk, P38 and JNK in SKBR-3 and CT-26 tumor cells, whereas Ipilimumab and ID-1 increased the phosphorylation of Erk in NK cells." (PMID 34201082, 2021). "In contrast, NR4A1 knockout promoted tumor growth coincident with increased ID1 expression in tumor tissues." (PMID 33990575, 2021). "Recent studies suggest that ID1 is a strong prognostic biomarker for ccRCC and link its up-regulation with poor survival and high probability of tumor metastasis." (PMID 34638458, 2021). "In high TGFβ signal conditions, Nur77 acts as a tumor promoter by amplifying the effect of TGFβ on ID1 induction." (PMID 33990575, 2021). "In contrast to ID1, little data are available about the contribution of the other ID proteins to tumor malignancy." (PMID 33514024, 2021). "GO-term analysis showed that the increase was enriched at pathways for cell mobility and invasion, in agreement with previous finding that ID1 promotes tumor cell migration and Matrigel invasion." (PMID 34820369, 2021). "We detected high mRNA expression of the four ID genes in all cell lines, including the non-tumor cell line 184A1, which indeed showed significantly higher expression of ID1 and ID3 than all the tumor cell lines (all p ≤ 0.03)." (PMID 33514024, 2021). "Consistent with the inverse correlation of Nur77 and ID1 expression was our finding that TGFβ signal was low in these tumor tissues." (PMID 33990575, 2021). "In order to evaluate the safety of the novel PD-L1_1 and ID-1 mAbs, we investigated their effects on human fetal cardiomyocytes (HFCs) co-cultured in presence of hPBMCs, and compared their anti-tumor effects with eventual cardiac side effects." (PMID 35008285, 2021). "In turn, ID1 supports tumor growth in hypoxia in vitro and in xenografts in vivo, conferring adaptive survival response and resistance." (PMID 34820369, 2021). "The activation and participation of the ID family, especially ID1, in tumor development have been widely studied in several tumor types." (PMID 33514024, 2021). "In contrast, FGF activates MAPK signaling and bypasses the AR in promoting CRPC tumor growth by inducing the expression of inhibitor of differentiation 1 (ID1)." (PMID 35008817, 2021). "The DNA-binding protein inhibitor ID-1 (ld1) is overexpressed in tumours and inhibits tumour angiogenesis in mice." (PMID 33865381, 2021). "Our group has shown that the reduction in glioblastoma tumour formation after inhibition of inhibitor of DNA-binding 1 (ID1) is mediated by downregulation of EGF and downstream ERK1/2 signalling." (PMID 34205450, 2021).
tumor (continued). "A high expression of Id1 and Id3 has been found in many types of cancer, both in the vasculature and in tumor cells." (PMID 34771577, 2021). "In conclusion, our results support that ID1 and ID4 have a role as pro-oncogenes in BC and are associated with tumor aggressiveness in BC subtypes." (PMID 33514024, 2021). "In this study, we examined the expression of ID proteins (ID1, ID2, ID3, and ID4) in BCa tissues and found that ID2 expression was downregulated and associated with tumor stage and survival." (PMID 34746132, 2021). "Isolated inhibition of Id1 in both tumor and host cells enhanced the frequency of tumor-infiltrating CD8+ T cells." (PMID 33126649, 2020). "The Id1+/GFP+ cells in the Id1C3-Tag model are predominantly of the CD29+/CD24+ phenotype, with a 1.6-fold higher proportion of cells expressing both CD29 and CD24 compared to the Id1−/GFP− cells which comprise the bulk of the tumor." (PMID 32766238, 2020). "Many other compounds exert their anti-tumor function via Id1-related signaling pathways or are found possessing effective regulation on Id1." (PMID 32410828, 2020). "Numerous drugs were found exerting their anti-tumor function through Id1-related signaling pathways, such as fucoidan, berberine, tetramethylpyrazine, crizotinib, cannabidiol and vinblastine." (PMID 32410828, 2020). "Id1/GFP+ cells (1/68) showed more than a 4-fold significant increase (p-value 0.0221) in tumor initiating cell frequency over Id1/GFP− cells (1/314) after serial passage." (PMID 32766238, 2020). "At day 14 after treatment initiation, we observed a very significant decrease in tumor growth in Id1 knockout mice treated with an anti-PD1 monoclonal antibody (Id1+/+/anti-PD-1, p = 0.0029; Id1+/+/DPBS, p < 0.0001)." (PMID 33126649, 2020). "IHC analysis showed that 15% of 4T1 tumor cells express high levels of Id1, and 35% have intermediate levels of Id1 expression, whereas the expression of Id3 was found in most of the cells." (PMID 32766238, 2020). "And the inhibition of Id1 enhances the effect of temozolomide, delays tumor recurrence, and prolongs survival." (PMID 32410828, 2020). "HPSE2 also promotes tumor suppression by downregulating the transcription factor Id1, further inhibiting heparanase activity and stimulating endoplasmic reticulum stress." (PMID 32175269, 2020). "Animals injected with Id1-depleted Lacun3 cells and treated with anti-PD-1 agent experienced a significant tumor growth impairment (Id1sh/DPBS n.s; pLKOsc/anti-PD-1 p = 0.0037; pLKOsc/DPBS p = 0.0174)." (PMID 33126649, 2020). "Overall, Id1 represent a promising target of anti-tumor therapeutics based on its potent promotion effect to cancer." (PMID 32410828, 2020). "Five and sixty percentage of cells in the Id1C3-Tag tumor were stained positive for Id1 and Id3 expression, respectively, as observed by IHC." (PMID 32766238, 2020). "Compared with controls, cells with overexpression of ID1 enhanced the tumor growth, whereas cells with knockdown of ID1 retarded the growth of tumor." (PMID 32080166, 2020). "We found that the expression of LC3B and ATF6 appeared to be positively correlated with ID1 expression in xenograft tumor tissues." (PMID 32080166, 2020). "The most plausible biological mechanism behind this finding is that combined Id1/PD-1 inhibition favors tumor infiltration by activated immune cells." (PMID 33126649, 2020). "Curcumin inhibited the mRNA and protein levels of inhibitor of DNA-binding 1 (Id1), which controls tumor aggressiveness." (PMID 33182828, 2020). "ID1 plays an important role in tumor cell differentiation and proliferation, as well as in tumor angiogenesis, and metastasis." (PMID 33324542, 2020).
tumor (continued). "Our in vivo experiments in which Id1 was silenced in tumor cells, host cells, or in both revealed the important role of Id1 expression in tumor and host cells in the antitumor activation of the immune system." (PMID 33126649, 2020). "Combining Id1 inhibition with anti-PD-1 treatment produced a clear synergistic effect that was more effective than either strategy alone in terms of tumor growth impairment and overall survival." (PMID 33126649, 2020). "More interestingly, CD8+ T cell depletion led to tumor growth phenotype restoration due to a significant reduction in the efficacy of PD-1 blockade, despite inhibition of Id1 and anti-PD-1 monoclonal antibody administration." (PMID 33126649, 2020). "We were able to isolate Id1+ tumor cells with a high degree of purity by FACS based on GFP expression followed by q-RT PCR." (PMID 32766238, 2020). "Id1-/- mice treated with the anti-PD-1 monoclonal antibody showed a significantly reduced tumor growth and longer survival in comparison to results seen in control groups (Id1-/-/DPBS p = 0.0283; Id1+/+/anti-PD-1 p = 0.0039; Id1+/+/DPBS p < 0.0001)." (PMID 33126649, 2020). "Id1+ cells are enriched for self-renewal in tumorsphere assays in vitro and for tumor initiation in vivo." (PMID 32766238, 2020). "Id1 is a promising target of anti-tumor treatment as many compounds exert anti-tumor properties by mediating Id1-related pathways." (PMID 32410828, 2020). "Co-culture assays using CD8+ cells and tumor cells showed that T cells present a higher antitumor effect when tumor cells lack Id1 expression." (PMID 33126649, 2020). "Our results showed that baicalein significantly reversed high phosphorylation of Src in tumor bearing mice indicating that baicalein inhibits Id1 in an Src dependent manner (P<0.0001)." (PMID 30949224, 2019). "The list of top upregulated genes in R1 cell-derived tumor xenograft versus parental cell-derived tumor xenograft also included ID1 and BMP4." (PMID 31013771, 2019). "This study firstly demonstrates that baicalein inhibits tumor growth in orthotopic human NSCLC xenografts via targeting Src/Id1 pathway." (PMID 30949224, 2019). "To explore mechanism of the anti-tumor effect of baicalein, we detected Id1 expression in each group as Id1 is an essential tumor promoter which promotes the proliferation of tumor cells and facilitates tumor growth." (PMID 30949224, 2019). "When compared with lungs of normal mice, lungs of tumor bearing mice expressed higher Id1 protein (P<0.0001) and baicalein significantly inhibited the Id1 expression level (P<0.0001)." (PMID 30949224, 2019). "Using immunohistochemistry, we confirmed ID1 overexpression in the resistant cell-derived tumor xenograft at the protein level." (PMID 31013771, 2019). "Cox regression analysis revealed that increased Id-1 expression was only significantly correlated with tumor differentiation." (PMID 31250351, 2019). "In our study, tumor burden increased the expression of Id1 and baicalein significantly inhibited its expression time dependently, and thus proliferation and metastasis of tumor cells were suppressed." (PMID 30949224, 2019). "In light of our results, we propose baicalein as a promising adjuvant therapy phytochemical and Id1 and its mediators as candidates for targeted anti-tumor therapeutic strategies." (PMID 30949224, 2019). "Overexpression of Id1 protein has been found in many types of human cancer, which correlated with tumor progression and unfavorable prognosis." (PMID 30949224, 2019). "In our study, we observed ID1 protein was down-regulated in 15 out 20 HCC tumors compared to matched non-tumor tissues." (PMID 30154433, 2018). "In light of our current data it will be important to investigate in what tumor contexts ID1 is required for EMT, and more broadly how the TGF-β–SMAD1/5 pathway contributes to different aspects of tumorigenesis." (PMID 29376829, 2018).
tumor (continued). "It was thus exciting to discover that in addition to increased recruitment of VEGFR1+ BMDCs, there was upregulation of CXCL5 in the lungs of nude mice xenografted with Id1-expressing ESCC tumours." (PMID 28186102, 2017). "Bone marrow cells transplanted from nude mice bearing Id1-overexpressing oesophageal tumours enhance tumour growth and metastasis in recipient mice, whereas systemic administration of VEGFR1 antibody abrogates these effects." (PMID 28186102, 2017). "In the present study, we found that Id-1 overexpression is significantly correlated with tumor progression and poor survival in NSCLC patients." (PMID 29233161, 2017). "mRNA and protein analyses confirmed that YM155 downregulated the tumour promoters BIRC5 and ID1 and upregulated the tumour suppressors FOXO1 and CYLD." (PMID 28582447, 2017). "Here, our findings showed that Id-1 expression remarkable increase in NSCLC tissues compared to the corresponding non-tumor tissues." (PMID 29233161, 2017). "We also found that high Id-1 expression in tumor tissues is significantly correlated with tumor progression and poor survival in NSCLC patients." (PMID 29233161, 2017). "Accordingly, Bcl3 knockdown results in decreased Id1 and Id2 expression, with tumor cells becoming more sensitive to chemotherapeutic drug-induced apoptosis." (PMID 28122577, 2017). "The results showed higher microvessel density in the Id1-overexpressing tumour xenografts, compared with tumours that expressed Id1-shIGF2 or control vectors." (PMID 28186102, 2017). "Src tyrosine kinase is suggested to promote tumor aggressiveness through BMP2-induced Id1 expression." (PMID 28122577, 2017). "Taken together, the tumor-promoting effects of Id-1 in NSCLC cells is at least partly through activation of NF-κB signaling pathway." (PMID 29233161, 2017). "Bioluminescent imaging showed that lung metastasis occurred most rapidly in the mice bearing Id1-expressing tumour, and that treatment with MF-1 to inactivate host VEGFR1 substantially reduced lung metastasis." (PMID 28186102, 2017). "We observed that lung metastasis developed most rapidly in the group injected with cancer cells mixed with bone marrow donated by mice bearing Id1-overexpressing tumour xenografts, and that selective VEGFR1 blockade using MF-1 suppressed lung metastasis." (PMID 28186102, 2017). "Taken together, these data showed that Id1-induced IGF2 from primary tumours can affect the tumour micro- and macroenvironment by systemically activating and mobilizing VEGFR1+ BMDCs to facilitate tumour growth and metastasis." (PMID 28186102, 2017). "The results showed obvious increase of VEGF immunostaining in the stroma of Id1-overexpressing tumours." (PMID 28186102, 2017). "Here, we found that blocking NF-κB signaling pathway using JSH-23 attenuated the Id-1-induced tumor cell metastasis, provide novel evidence to support further explorations into the use of NF-κB inhibitors in NSCLC cancer therapy." (PMID 29233161, 2017). "Id-1/Id-2 further binds to p62, and be transported to autolysosomes for degradation, thus regulating the differentiation of tumor cells and reducing the proportion of stem cell-like cancer cells." (PMID 29079782, 2017). "In medulloblastoma the Id2 and Id3 proteins are overexpressed and promote tumor cell proliferation, whereas the Id1 protein has been found to be expressed in the tumor vessels, thus promoting tumor angiogenesis." (PMID 28122577, 2017). "We found an enrichment of GFP+/VEGFR1+ cells, but not the other subpopulations, in the bone marrow of mice bearing Id1-expressing tumours, compared with the Id1-shIGF2 and the vector control groups." (PMID 28186102, 2017). "Our results showed that addition of polyethylenimine (PEI) to collagen can facilitate entry of Id1-siRNA into target cells, prolong the silencing effect, and further inhibit tumor growth both in vitro and in vivo." (PMID 27029190, 2016).